BRAF (B-Raf proto-oncogene, serine/threonine kinase)
Diseases named in the same sentence as BRAF in open-access papers (continued):
Sharing a sentence is not in itself a finding about the gene and the disease.
melanoma (continued). "In contrast, NRAS Q61K- and Q61R-mutated and BRAF wild-type melanoma cells were unaffected by the KD." (PMID 35034957, 2022). "The most promising targeted therapies include the BRAF inhibitors vemurafenib and dabrafenib, which were approved for the treatment of metastatic and unresectable BRAF-mutated melanomas in 2011 and 2013, respectively." (PMID 35383224, 2022). "We show here that the Aryl hydrocarbon Receptor (AhR) transcription factor directly regulates the gene expression program associated with the acquisition of resistance to BRAF inhibitor (BRAFi) in melanoma." (PMID 36305167, 2022). "Later, the BRAF inhibitor dabrafenib was also approved for melanoma patients with the BRAF mutation." (PMID 36551302, 2022). "Previous studies have showed that BRAF mutations are associated with a worse prognosis in colorectal cancer and a better prognosis in melanoma." (PMID 35365157, 2022). "Since the development of first generation BRAF inhibitors (BRAFi), vemurafenib in 2011 and dabrafenib in 2013, melanoma patients with BRAFV600 mutations highly benefited from this targeted therapy (TT)." (PMID 36230853, 2022). "In particular, in BRAF-mutated melanomas, CAF-produced HGF was able to activate the MAPK and AKT pathways in tumor cells, thus compensating for BRAF switch-off and sustaining resistance." (PMID 36324182, 2022). "The first MEK1/2 inhibitor PD098059 was followed by trametinib (MEKinistTM), as the first clinically useful MEK inhibitor applied as agent to treat BRAF-mutated melanomas." (PMID 36048281, 2022). "Loss of PTEN has been associated with resistance to BRAF inhibitors and decreased overall survival in melanoma." (PMID 36333792, 2022). "Due to the relative rarity and great variety of non-V600 BRAF mutations in melanoma, development of a randomized controlled trial for targeted therapies remains challenging." (PMID 35380338, 2022). "This was a retrospective single-center analysis of 46 patients (21 female, 25 male) with advanced melanoma who underwent circulating tumor DNA (ctDNA) BRAF mutation testing." (PMID 35159044, 2022). "The success of kinase inhibitors as targeted therapy was triggered by the detection of activating somatic BRAF V600 mutations in melanoma cells." (PMID 35059911, 2022). "We first defined a gene signature based on the top 200 most significantly upregulated genes for BRAF V600E mutations in primary TCGA melanoma samples." (PMID 35044091, 2022). "The V600E mutation comprises 80% of BRAF-related melanomas and is seen mostly in younger patients in anatomical sites protected from sun exposure." (PMID 36232957, 2022). "Together, these data demonstrate that combinations of CDK12 and IKKβ inhibitors are synthetic lethal for BRAF-mutated melanoma cells." (PMID 36309522, 2022). "We generated melanoma cells resistant to vemurafenib from primary and metastatic cell lines, both with BRAF V600E mutations." (PMID 36077308, 2022). "Mutations at codon 600 of BRAF gene is widespread in melanoma (mostly V600E), making it a potential therapeutic target." (PMID 36210843, 2022). "The BRAF mutation has been described in 40–50% of all human melanoma cases and is more commonly seen in younger patients." (PMID 36686160, 2022). "For example, the BRAF V600E is the most frequent genetic cause of melanoma, which is responsible for the increased proliferation and metabolic reprogramming of melanoma cells." (PMID 36289813, 2022). "PTEN inactivation has been linked to resistance to BRAF inhibitors and immunotherapy in melanoma patients." (PMID 36614156, 2022). "According to Cisilotto and collaborators, in the SK-MEL-28 BRAF-mutated melanoma cell line, Brazilian propolis increased ROS accumulation, demonstrating that propolis had a pro-oxidant function." (PMID 35684471, 2022). "PTEN loss and the subsequent increase in AKT signaling limits BRAF inhibitor-induced apoptotic responses in melanoma." (PMID 35806358, 2022).
melanoma (continued). "Other entities have followed—for example, therapeutic implications of BRAF (B-Raf Oncogene) mutations in patients suffering from malignant melanoma are usually discussed within the dermatologic tumor board." (PMID 36291825, 2022). "Agents targeting aberrant signaling in melanomas with BRAF mutations have been shown to significantly improve the survival rate of melanoma patients." (PMID 35954498, 2022). "In melanomas, the oncogene BRAF is the most commonly mutated (more than 50% of tumors), and 90% of all activating BRAF mutations involve V600E substitution." (PMID 36613587, 2022). "The study showed that the BRAF V600 mutation is an independent prognostic factor for the recurrence of malignant melanoma after surgery." (PMID 35406444, 2022). "They found that in patients with BRAF-mutated melanoma brain metastases, first-line treatment with BRAF/MEK inhibitor therapy improved overall survival compared to patients treated with first-line therapy with anti-PD1 (P = 0.043)." (PMID 35311078, 2022). "BRaf proto-oncogene, serine/threonine kinase (BRAF) is the most frequently mutated serine-threonine protein kinase involved in the pathogenesis of melanoma and is mutated in most melanoma and melanocyte lesions." (PMID 36185198, 2022). "Approximately half of the patients with melanoma have BRAF mutations that result in constitutive ERK activation, thereby promoting the proliferation and migration of tumor cells." (PMID 36009363, 2022). "Rare activating mutations account for approximately 3.4 to 14% of BRAF-mutated melanomas [2, 5•, 8, 11–12]." (PMID 35380338, 2022). "NRAS mutations and BRAF amplification are also often identified in genetic analysis of melanoma samples." (PMID 35565444, 2022). "Of note, several CDKN2A patients have been reported with melanomas with coexisting BRAF and NRAS mutations, which is uncommon in sporadic melanomas." (PMID 35372037, 2022). "This tendency was also observed in BRAF mutated primary tumors of patients who died from melanoma, but the decrease was significant only for miR-125b and miR-205 (p-value 0.0078 and 0.0398, respectively)." (PMID 35326682, 2022). "Among BRAF-mutated melanomas, 12 patients started PD1-based therapy and 88 started BRAF+MEK inhibitors in the first line, and their outcome correlated with the presence of symptoms associated with MBM." (PMID 36497248, 2022). "Mutations in the BRAF gene occur most commonly in melanocytes in sun-exposed skin and account for approximately half of all melanomas." (PMID 35323214, 2022). "Some studies have shown that the serial determination of the BRAF mutation in circulating tumour DNA (ctDNA) can help predict the response to treatments for patients with melanoma, but this technique has very limited implementation." (PMID 35203494, 2022). "In this study, we analyzed tumor cell killing by ascorbate in melanoma cells with a focus on BRAF mutated melanoma cells and the interaction with the BRAFi vemurafenib." (PMID 35406796, 2022). "The presence of activating BRAF mutations in melanoma cells is a cornerstone of the antitumor activity of BRAF/MEK inhibitors." (PMID 35159044, 2022). "For patients that have melanoma with an activating BRAF mutation, both treatment modalities are available, and typically the choice of which therapy is used first is at the discretion of the treating oncologist." (PMID 35323326, 2022). "The increased PMCA4b level after HDAC inhibition strongly reduced cell migration of A375 BRAF mutated melanoma cells." (PMID 35328746, 2022). "To determine the role of CDK12 in melanoma, we performed RNA-sequencing (RNA-seq) on two BRAF-mutated melanoma cell lines (A375 and Colo829) treated with CDK12 inhibitors (THZ531; 500 nM) for 6 h." (PMID 36309522, 2022).
melanoma (continued). "In BRAF mutated melanoma cell lines, the MEK/ERK pathway promotes the constitutive activation of mTOR through the p90 ribosomal S6 kinase RSK, inhibition of which abrogates tumor growth in mouse models." (PMID 35912100, 2022). "We investigated the ONC ability to modulate the expression of 16 onco-suppressor microRNAs (miRNAs) in the A375 BRAF-mutated melanoma cell line." (PMID 35163570, 2022). "It turned out to be a melanoma based on the genomic profile and presence of a BRAF p.Val600Glu mutation." (PMID 35053600, 2022). "V-Raf murine sarcoma viral oncogene homolog (BRAF) mutations have been described in 8% of cancer, with higher incidence reported in melanoma (40–60%), papillary thyroid carcinomas (30–70%), and colorectal cancers (5–20%)." (PMID 35454926, 2022). "In contrast, melanomas with WT BRAF, NRAS and NF1 that are driven by activating KIT mutations can be treated with the RTK inhibitor imatinib, yielding response rates of 16–30%; however, most of these responses were partial and transient." (PMID 35234863, 2022). "We analyzed the expression of the Activin-A encoding gene INHBA in melanoma patients and the influence of its gain- or loss-of-function on the immune infiltration and growth of BRAF-driven YUMM3.3 and iBIP2 mouse melanoma grafts and in B16 models." (PMID 35580932, 2022). "A previous study has detected many genes against BRAF mutation in melanoma, including significant cell cycle controls, tumour permanence enzymes, and microphthalmia-related transcription components." (PMID 36551688, 2022). "MEK inhibitors targeting the MAPK pathway are used in combination with BRAF inhibitors in melanoma, metastatic lung cancer, and metastatic anaplastic thyroid cancer when a BRAF V600E or V600K mutation is present." (PMID 35343367, 2022). "BRAF-mutated melanomas are characterized by more aggressive clinical features compared to wild-type ones." (PMID 36016960, 2022). "Tumor proliferation in up to half of all melanomas relies on activating BRAF mutations, of which 70–80% account for mutations in V600E and another 10–20% for the less active V600K [3••, 4–8]." (PMID 35380338, 2022). "Testing for the presence of somatic BRAF mutations in melanoma is a crucial step in diagnosis and the qualification for treatment." (PMID 35159044, 2022). "This approach is based on the observation that BRAF-mutated melanoma cells have a low T cell infiltration and a high level of IL-6, IL-10, and VEGF, which increase the number of Tregs or myeloid-derived suppressor cells within TME." (PMID 35334544, 2022). "Nearly half of melanomas harbor mutations of the v-raf murine sarcoma viral oncogene homolog B (BRAF) gene, leading to activation of the mitogen-activated protein kinase (MAPK) signaling pathway." (PMID 36202798, 2022). "Because of the prevalence of the BRAF mutations in melanoma, one of the most successful targeted therapies for BRAF mutated melanomas are BRAF kinase inhibitors such as vemurafenib." (PMID 35883549, 2022). "We found that depletion of the ERK phosphatase DUSP4 induces oncogene overdose and loss of fitness in both drug-naive and drug-resistant BRAF-mutant melanoma cell lines." (PMID 35580987, 2022). "These mutations, especially BRAF V600E, are observed in approximately half of melanoma cases, and this specific mutation represents 90% of all known BRAF mutations." (PMID 35056382, 2022). "To date, this compound has been used in the treatment of patients with unresectable or metastatic BRAF V600E/V600K-mutated melanoma." (PMID 36358795, 2022). "BRAF inhibitor was considered the foundation of BRAF mutated melanoma treatment, and have demonstrated success and enhanced patient survival." (PMID 36531226, 2022). "ddPCR assays were performed to detect BRAF/NRAS mutations in plasma from 161 stage II/III melanoma patients enrolled in the AVAST-M adjuvant trial." (PMID 36579573, 2022).
melanoma (continued). "BRAF V600 hotspot mutations are found in around 40–60% of all melanomas, and these mutations are present in about 67–90% of all acquired nevi." (PMID 36143375, 2022). "This was consistent with the fact that melanoma with BRAF or NRAS mutations were highly dependent on the MAPK pathway and showed a favorable response to MAPK inhibitors." (PMID 34718347, 2022). "More than 15,500 genes were specifically expressed in a BRAF V600E melanoma cell line to assess the influence of each gene on the susceptibility of melanoma to MAPK pathway inhibition in a systematic gain-of-function resistance study." (PMID 35805104, 2022). "NRAS-mutated melanoma is distinct from BRAF-mutated melanoma in clinical presentation and prognostic features." (PMID 36402789, 2022). "Dabrafenib is a single-agent treatment for patients with BRAF V600E mutation-positive advanced melanoma." (PMID 36221095, 2022). "Oncogenic BRAF mutations have been detected in approximately 6% of human cancers, with most occurring in hairy cell leukemia (> 97%), melanoma (40–50%), thyroid cancer (30–50%), colorectal cancer (10%), and non-small cell lung cancer (3–5%)." (PMID 36585710, 2022). "BRAF inhibitor drug resistance has been a long-time challenge in the treatment of melanoma with BRAF V600E mutation." (PMID 36358868, 2022). "Melanoma is the most lethal form of skin cancer, with BRAF mutations occurring in about 50% of cases." (PMID 35440004, 2022). "Although there are many unanswered questions related to advanced-stage BRAFV600E melanomas, the major indecision in current practice is the choice between BRAF/MEK inhibitors or immunotherapy for metastatic or high-risk disease patients." (PMID 35053476, 2022). "Although covered by industry, in 2021, only 88 BRAF mutation tests (mainly for melanoma) were performed, although there were 2051 people diagnosed with melanoma." (PMID 36589179, 2022). "Melanoma genomes have the highest mutation rate, with V-RAF murine sarcoma viral oncogene homolog B (BRAF) mutations being the most prevalent, which occur in roughly 40–60% of melanoma cases." (PMID 35684471, 2022). "The recently published TRICOTEL phase 2 trial reported that atezolizumab plus vemurafenib and cobimetinib provided promising intracranial anti-tumor activity and acceptable toxicity in patients with BRAF(V600)-mutated melanoma." (PMID 36698407, 2022). "Altogether, this suggests that the three tested melanoma cell lines show good response to AXLi, and that their sensitivity to BRAFi depends on the BRAF mutation status." (PMID 35332208, 2022). "Acral melanomas with BRAF class 1 mutations, especially V600E, had fewer structural variations and focal amplifications, than those without and thus resemble cutaneous melanomas." (PMID 35706047, 2022). "Dabrafenib is a kinase inhibitor approved for the treatment of metastatic or unresectable melanoma with a BRAF V600E or V600K mutation and as an adjuvant treatment of subjects with melanoma plus lymph node involvement (BRAF V600E- or V600K-mutated)." (PMID 35742834, 2022). "In cancers such as melanoma, BRAF is typically mutated at the V600 codon, allowing for the BRAF kinase activation in the absence of both dimerization and an active RAS." (PMID 35178568, 2022). "The most frequently observed mutation in melanoma, present in almost 60% of melanomas, is the activating mutation V600E in the BRAF gene." (PMID 36551563, 2022). "Accordingly, 18fluorine-deoxyglucose positron-emission tomography (18FDG-PET) data show that the glycolytic phenotype is increased in BRAF-mutated melanoma patients." (PMID 35163570, 2022). "BRAF and MEK targeted therapies are an option for the 40–50% of melanoma patients with BRAF mutated tumors, however drug resistance is a predictable event within the first year of treatment." (PMID 36358601, 2022). "Presently, the presence of a BRAF V600 mutation is the only validated predictive biomarker for melanoma patients." (PMID 36613491, 2022).
melanoma (continued). "The efficacy of this combination as a first-line therapy was compared to vemurafenib monotherapy in an open-label, phase III clinical trial of patients with either BRAF V600E-mutated or BRAF V600K-mutated advanced melanoma." (PMID 35954441, 2022). "One of the most important systems is the MAPK cascade, which is activated by BRAF signals to promote the genesis of melanoma in fish with the BRAFV600E mutation." (PMID 36142160, 2022). "The BRAF gene is an oncogene that, when mutated in melanoma, is always constitutively activated, and therefore upregulates the MAPK/ERK pathway." (PMID 36143375, 2022). "In the BLISH, we focused on recapitulating the hallmark events of melanoma metastasis and evaluating the anti‐metastatic effect of BRAF/PI3K combined inhibition, as well as investigating the tumor‐induced endothelial disruption." (PMID 36026581, 2022). "The pathogenesis of malignant melanomas is very complex, including a series of complicated interactions among external events and endogenous triggers, genetic mutations of BRAF, NRAS, and KIT, as well as endogenous and immune-related factors of the tumor." (PMID 35220953, 2022). "In general, melanoma can be classified into four subtypes based on the mutation carried in the tumour, i.e., BRAF, NRAS, NF1 or triple wild type." (PMID 35740696, 2022). "Clinically, a more aggressive course of disease can often be observed in class II and III BRAF-mutated melanomas than in class I melanomas [14••]." (PMID 35380338, 2022). "As an ATP noncompetitive selective inhibitor of MEK1/2, PD-0325901 displays significant antitumor effects in melanoma, head and neck, and BRAF-mutated papillary thyroid cancer." (PMID 36532035, 2022). "BRAF is mutated in 60% of melanomas and drives oncogenes for a variety of malignancies such as colorectal, ovarian, and papillary thyroid cancer." (PMID 35620280, 2022). "Approximately 50% patients with melanoma and papillary thyroid carcinoma carry a variant of the BRAF gene." (PMID 35893795, 2022). "There is a discrepancy regarding the prognostic value of mutations in the BRAF gene in melanoma patients." (PMID 35326682, 2022). "Transcriptome sequencing analysis of tissue samples from melanoma patients indicated that mutations closely related to melanoma progression mainly included BRAF mutation, NRAS mutation and NF1 mutation." (PMID 36601121, 2022). "In the modern era, there is a debate about which is the best first line treatment between targeted therapies and immunotherapy in stage IV BRAF-mutated melanoma patients." (PMID 36046043, 2022). "Our work shows that melanomas affected by the BRAF V600K variant have a similar clinical and dermoscopic presentation but a more aggressive behaviour than those with BRAF V600E." (PMID 35080260, 2022). "In our study, we aimed to analyze the clinical utility of ctDNA for BRAF mutation testing in patients with melanoma in routine clinical practice." (PMID 35159044, 2022). "To investigate this question, we collected plasma samples pre- and post-treatment with MAPK inhibitor (MAPKi) therapy from patients with late-stage melanomas that harbored a BRAF V600E mutation." (PMID 35565240, 2022). "For example, BRAF inhibition in melanoma patients has been shown to cause CAF-mediated ECM remodeling, which supports melanoma growth and promotes BRAF-inhibitor resistance by upregulating integrin β1/FAK/Src signaling." (PMID 36671452, 2022). "BRAF-mutated melanoma cells were extremely vulnerable to fisetin treatment, and this was related to a reduction in the phosphorylation of ERK1/2 as well as MEK1/2." (PMID 36558146, 2022). "Tissue stiffness and matrix composition are involved in the response of melanoma cells to the BRAF inhibitor (BRAFi) through melanoma-associated fibroblasts (MAFs)." (PMID 35565234, 2022). "According to clinical studies, trametinib, an FDA-approved MEK1/2 inhibitor, was used in tumors with BRAF-activating mutations including melanoma, non-small cell carcinoma and thyroid cancer." (PMID 35892850, 2022).